WNT5A (Wnt family member 5A)
Diseases named in the same sentence as WNT5A in open-access papers (continued):
Sharing a sentence is not in itself a finding about the gene and the disease.
tumor (continued). "It has been reported that Wnt5a may promote tumor progression through inducing actin reorganization and increasing cell motility via activating the PKC and calcium signaling pathway." (PMID 22655072, 2012). "The present data (strong expression of Wnt5a at the edge and in surrounding stroma, focal polarised intracellular distribution of Fzd3 within the tumors) suggests the existence of Wnt5a gradients acting from the tumor margin (as well as Wnt5a expressing stroma cells, fig." (PMID 22384081, 2012). "Nonetheless, the role of Wnt5a in cancer is controversial, some reports suggesting that Wnt5a may act as tumor suppressor by antagonising canonical Wnt signalling." (PMID 22384081, 2012). "We next studied the spatial relationship of Wnt5a, Fzd3, and Fzd5 in individual tumor samples." (PMID 22384081, 2012). "A large number of studies have indicated that Wnt5a commands a tumor-suppressing effect." (PMID 22655072, 2012). "Dysregulated Wnt5a signalling facilitates invasion of multiple tumor types into adjacent tissue." (PMID 22384081, 2012). "Conversely, Wnt5a functions as a tumor suppressor in colon, thyroid, and hepatocellular cancers." (PMID 22655072, 2012). "However, it cannot be excluded that Wnt5a exerts different effects on tumor progression in different stages of the disease." (PMID 22039506, 2011). "The strong and independent associations of Wnt5a methylation with both MSI and BRAF V600E suggest that this event may be a marker of MSI/CIMP-high tumours, which seem to be a particularly favourable CRC subset in these studies." (PMID 21587258, 2011). "Wnt5a significantly correlated with VEGF, a marker for angiogenesis, indicating that Wnt5a might be related to tumor growth." (PMID 22039506, 2011). "The hypothesis that Wnt5a has a tumor suppressive function was further supported by our invasion data in three of four PCa cell lines investigated." (PMID 22039506, 2011). "ROR2/WNT5A upregulation could be advantageous to cancers driven by non-canonical Wnt signalling, while their epigenetic downregulation would benefit tumours, such as colon and haematopoietic cancers, that are driven by canonical Wnt signalling." (PMID 20591152, 2010). "Furthermore, DNIIR and Wnt5a-/- tumours show similarities to tumours induced by activation of Wnt/β-catenin in their ability to expand a K6 progenitor cell population in addition to a unique K14 expressing population." (PMID 19344510, 2009). "By western blotting, Wnt5a protein levels were reduced in tumours with altered TGF-β responsiveness in both the MMTV-neu and MMTV PyVmT models suggesting that, in addition to regulating Wnt5a in normal mammary development, TGF-β can act to maintain Wnt5a expression during tumour formation." (PMID 19344510, 2009). "Nevertheless, recent work has pointed to a critical role of Wnt-5a in malignant progression, but whether it is afforded by a tumour-suppressing effect or an oncogenic effect is questionable." (PMID 19603030, 2009). "Moreover, subcellular fractionation and western blotting showed an increase in β-catenin in the nuclear compartment of cells in the Wnt5a-/- tumours." (PMID 19344510, 2009). "Unsurprisingly, given its functional promiscuity, investigations to elucidate the role of Wnt-5a in cancer have shown paradoxical results and studies indicate that it may have a tumour suppressing or an oncogenic effect depending on the cancer type." (PMID 19603030, 2009). "It will be important to further investigate the role of Wnt5a in HCC tumor progression." (PMID 19849855, 2009). "In addition to directly influencing cancer cell behavior, Wnt5a also shapes an immunosuppressive tumor microenvironment by skewing immune cell profiles, favoring the presence of M2 macrophages and regulatory T cells while reducing cytotoxic T cells and M1 macrophages." (PMID 40330466, 2025).
tumor (continued). "In GC, overexpression of Wnt ligands (Wnt2, Wnt3, and Wnt5A) and receptors (FZD7 and LRP5/6) is associated with more advanced disease, poorer prognosis, and elevated metastatic potential, while β-catenin and reduced APC expression further underline more aggressive tumor behavior." (PMID 40943055, 2025). "Furthermore, Wnt5a signaling promotes the expression of PD-L1 on tumor cells and myeloid-derived suppressor cells (MDSCs), reinforcing an immunosuppressive microenvironment that dampens anti-tumor immunity." (PMID 40917745, 2025). "WNT5A produced by MSCs in MM can act as a growth factor for tumor cells and increase osteoclast activity, which may explain the increased amount of WNT5A in this patient (although it does not explain the low levels of the protein in the other patients and in HD)." (PMID 40650009, 2025). "Furthermore, treating THP‐1 cells with PMA + IL‐4 + IL‐13 for 72 h resulted in a decrease in Wnt5a protein expression in HCT116 cells, which may be associated with its involvement in tumor cell differentiation‐related functions." (PMID 39302044, 2024). "Interestingly, WNT5A may also have tumor-suppressive effects by opposing the canonical Wnt pathway, which inhibits cell growth and migration." (PMID 39176352, 2024). "Besides, knockdown of WNT5A in CAFs inhibits tumor growth in vivo." (PMID 39054546, 2024). "Therefore, in certain types of cancer, Wnt5a is a suppressor of tumor growth." (PMID 39665023, 2024). "Furthermore, endothelial Wnt5A has been shown to promote retinal and tumour angiogenesis." (PMID 39496510, 2024). "This shows that WNT5A may be essential in controlling the tumor immune microenvironment." (PMID 39176352, 2024). "Altogether, the Wnt5a/JNK/β‐catenin signaling pathway activated by overexpressing Atg5 under autophagy‐deficient conditions may contribute to increased cell proliferation, migration, and tumor formation in vitro or in vivo." (PMID 38826147, 2024). "However, it is unclear whether TAMs produce sufficient levels of ROR2 to respond to WNT5A or whether they rely on CAF-transferred ROR2 similar to tumor cells." (PMID 37722040, 2023). "With WNT5A being one of only seven genes significantly upregulated in SIX1/2-Q177R tumors compared to other blastemal tumors in both expression datasets, it is a strong candidate for promoting tumor progression and the chemotherapeutic resistance associated with SIX1/2-Q177R." (PMID 37815464, 2023). "1,25 dihydroxy-vitamin D3 downregulates NRG1, WNT5A, PDGFC, genes associated with proliferation, and increases the expression of NFKBIA, TREM-1, genes involved in immune modulation, effects consistent with the anti-tumor effects of 1,25 dihydroxy-vitamin D3 in BC." (PMID 37046676, 2023). "Therefore, we tested Fzd4’s level and found that Lin28b could only be detected in both Wnt5a and Fzd4 high-‍expressed tumor cells lines, indicating that intact Wnt5a-Fzd4 pathway is essential for activation of Lin28b in PDAC." (PMID 37898598, 2023). "The WNT5a gene serves as an example of one of many possible genes that can be tracked within CTCs to potentially predict disease behavior; changes in its expression in CTCs may herald transitions in tumor behavior." (PMID 36230844, 2022). "Secreted WNT5a in the tumor microenvironment may also have an immunomodulatory role." (PMID 36230844, 2022). "However, as an oncoprotein, ROR1 can reemerge in hematological and solid tumors, especially in histologically advanced tumors, where ROR1 may promote tumor cell migration through Wnt5a signaling or interaction with other receptors." (PMID 35480093, 2022). "As a result of these mechanisms, the Wnt5A/ROR1 signaling axis plays a negative role associated with enhanced tumor cell migration or induces a transcriptional response leading to the expression of genes that contribute to cell proliferation, survival, EMT, or therapy resistance." (PMID 34376211, 2021). "Furthermore, Wnt5a knockdown impaired the pro-tumor roles of TAMs in vivo and in vitro." (PMID 32140070, 2020).
tumor (continued). "Other factors secreted by α-SMAhigh CAFs such as Ctgf, Pgf and Wnt5a have been implicated in cancer cell proliferation, migration, invasion, EMT and/or angiogenesis, suggesting that α-SMAhigh CAFs may promote tumor development and progression." (PMID 32455670, 2020). "Thus, Wnt5a mediated the pro-tumor effects of TAM through other soluble factors." (PMID 32140070, 2020). "Wnt5a is produced by tumor cells may act in an autocrine loop." (PMID 32586008, 2020). "One possibility is that Wnt5a might be expressed by cells residing in the tumor stroma." (PMID 32195251, 2020). "However, it is unclear whether Wnt5a affects the biological behavior of tumor cells through the crosstalk between TAMs and cancer cells." (PMID 32228612, 2020). "Therefore, the inflammatory factors in tumor microenvironment may play an important role in Wnt5a induction." (PMID 32228612, 2020). "Cav1 might play an important physiological role in the defence against tumour‐derived exosomes via the degradation of Fzd2, thereby suppressing Wnt5a‐driven malignant transformation or inhibition of tumour‐derived exosomes internalization through an unidentified mechanism." (PMID 29502342, 2018). "Moreover, Wnt5a heterozygosity promoted tumor multiplicity and pulmonary metastasis." (PMID 28491097, 2017). "However, WNT5A has variously been described as a pro or an inhibitor of tumor growth in bone." (PMID 27776343, 2016). "Wnt5a expression may play a stimulative role in the tumor invasion to the surrounding tissue." (PMID 26608372, 2016). "In contrast to CLL and ATL, WNT-5A may have tumor suppressive effects in ALL." (PMID 26514730, 2016). "According to this point, Wnt5a may play the role of tumor suppressor in PTL." (PMID 26608372, 2016). "In addition, tumor cell-derived Wnt5a was also involved in angiogenesis." (PMID 27608847, 2016). "Also in human samples, Wnt5a appeared to function as a tumor suppressor." (PMID 27571104, 2016). "Our hypothesis is that Wnt5a plays a tumor suppressor role in the early stage of disease." (PMID 26608372, 2016). "However, little correlation was found between Wnt5a-positive expression and other clinicopathological characteristics, such as age, tumor size, location, histological differentiation, pleura invasion, stage, metastasis, lymph node status, and therapy before surgery (P > 0.05)." (PMID 24999479, 2014). "Wnt5a is a non-canonical signaling Wnt that has been implicated in tumor suppression." (PMID 25401739, 2014). "Thus, we also analyzed the correlation between Wnt5a and VM, which could reflect the blood supply of tumor at some degree." (PMID 24999479, 2014). "We detected only minimal differences in expression of Sca-1 and K8, markers for luminal cells, in Wnt5a expressing tumors relative to the MMTV-Wnt1 controls, suggesting Wnt5a may specifically target cells in the tumor that express or are destined to express basal-like markers." (PMID 25401739, 2014). "Interestingly, the role of Wnt5a in carcinogenesis is still ambiguous, as it can exhibit tumour suppressor activities in some cancers, like thyroid, brain, breast and colorectal, but is aberrantly up-regulated and associated with tumour progression in cancers of the lung, stomach and prostate." (PMID 23505429, 2013). "Expression of Wnt5a by UC tumor cells may also be a predictor of an aggressive subgroup of UC." (PMID 23947922, 2013). "However, some evidence supports the hypothesis that Wnt5a acts as a tumor and developmental suppressor in other breast experimental systems." (PMID 22655072, 2012). "The strong expression of Wnt5a at the leading edge, as well as in tumor-surrounding stroma cells, in conjunction with the polarised expression of Fzd3 within the tumor mass suggest that Wnt5a gradients project into the tumor to enhance motility in distinct subpopulations." (PMID 22384081, 2012). "However, whether Wnt5a acts as a tumor-promoting or tumor-suppressing factor remains a debatable question." (PMID 23342259, 2012).
tumor (continued). "Besides, Wnt5a acts as an oncogene or tumour suppressor gene in a context-dependent manner." (PMID 23730201, 2012). "The possibility of Wnt5a to induce different downstream signaling events can at least in part explain the presence of reports suggesting an ambiguous nature of Wnt5a; having either a tumor suppressor or tumor promoting function depending on context and tumor type." (PMID 22039506, 2011). "As proposed for ROR2, WNT5A might also have either a tumour-promoting or-suppressing role." (PMID 20591152, 2010). "Upon determining that Wnt5a limits the accumulation of intracellular β-catenin in normal mammary epithelium and tumours, we speculated that tumours harboring DNIIR would also exhibit stabilised intracellular β-catenin, probably as a consequence of reduced Wnt5a levels." (PMID 19344510, 2009). "Several lines of evidence support the hypothesis that Wnt5a acts as a tumour suppressor." (PMID 19344510, 2009). "Therefore, Wnt-5a, in the presence of specific FZ isoforms, could promote tumour growth by activation of the cancer-promoting canonical Wnt signalling pathway." (PMID 19603030, 2009). "This metabolic-immune crosstalk highlights how Wnt5a-driven IDO1 activity facilitates immune escape and sustains metabolic plasticity, thereby supporting tumor progression." (PMID 40917745, 2025). "EC is characterized by elevated expression of multiple Wnt ligands (notably Wnt2, Wnt3, Wnt5A, and Wnt6) and FZD receptors, often correlating with poorer differentiation, higher potential of tumor invasion, and shorter survival." (PMID 40943055, 2025). "For instance, Wnt5a activates ROR2 in osteoblasts, promoting JNK signaling and RANKL production, thereby creating a continuous cycle of bone destruction and tumor growth." (PMID 40426987, 2025). "Fib-BMP5 was found mainly in the tumour samples, and was characterized by the elevated expression of SLC14A1, NRG1, and WNT5A." (PMID 41281745, 2025). "WNT5A promoters A and B were investigated in the U2OS and SaOS-2 OS cell lines, as well as in tumor tissues and normal osteoblasts." (PMID 40868849, 2025). "Consequently, the downregulation of WNT5A observed in PTSO-treated mice may not only indicate suppression of proliferative signaling, but also a direct impairment of CSC maintenance, potentially lowering the risk of tumor recurrence and therapy resistance." (PMID 41010517, 2025). "For instance, Wnt5a-FZD interactions enhance Ca2+-mediated cytoskeletal reorganization and cell motility, facilitating tumor invasion into surrounding tissues and dissemination to distant sites." (PMID 40376615, 2025). "Among the Wnt-related genes relevant to PCa, Wnt3a, Wnt5a, Fzd7, sFRP1, and ROR2 stand out due to their roles in modulating tumour behaviour under hypoxic conditions." (PMID 41007281, 2025). "In colorectal cancer, aberrant Wnt5a signaling correlates with elevated IDO1 expression and reduced infiltration of cytotoxic CD8+ T cells, indicating a more immunosuppressive tumor microenvironment." (PMID 40917745, 2025). "Among them, upregulated genes such as CAMK2N1, IGFBP4, RGS2, WNT5A, and CDH1 have both tumor suppressor and inhibitory effects on EMT." (PMID 39768220, 2024). "Further analysis of the subpopulations of tumor fibroblasts (FB0-FB8) revealed a marked heterogeneity in them in relation to Wnt5a expression." (PMID 38191909, 2024). "When STAT3 is silenced, it results in reduced expression of both Wnt5a and ROR1, leading to increased apoptosis in tumor cells." (PMID 39551787, 2024). "Tumor-enriched macrophages (CTSK+ and C1QC+ macrophage) and WNT5A+ inflammatory fibroblast states, which contribute to diverse aspects of tumorigenesis, were also found in the pro-tumorigenic community." (PMID 38744958, 2024). "MiR-129-5p suppressed angiogenesis, tumor invasion, and TMZ resistance by Wnt5a targeting in GBM cells." (PMID 38956588, 2024).
tumor (continued). "Tumor-bearing mice treated with Bm@PT/Enz-miR26a showed significant fluorescence of SFRP1 and decreased fluorescence of EZH2, WNT5A, and AR compared to other groups." (PMID 38566211, 2024). "For example, Wnt5a is able to secrete the chemokine CCL2 through the Wnt5a-CaMKII-ERK pathway, altering the tumor microenvironment and promoting tumor cell proliferation and migration." (PMID 39598398, 2024). "Molecules with tumor suppressor functions such as CAMK2N1, CDH1, IGFBP4, RGS2, and WNT5A were upregulated in MDA231 cells after their co-culture with DBMSCs in an IC setting." (PMID 39768220, 2024). "The downstream pathways of Wnt5a are planar cell polarity (PCP) and Wnt/Ca2 + pathways, which have a key role in cell physiology and tumor progression." (PMID 38956588, 2024). "Western blot indicated that WNT5A and HK2 were upregulated by CAFs in mice tumor, while decreased when WNT5A was silenced in CAFs." (PMID 39054546, 2024). "Although we did not detect LINC00313 over-expression in CCA tissues, the expression levels of ACTL6A, TCF7, WNT5A, AXIN2 and SULF2 were all increased in CCA human tumours (Fig. EV5B)." (PMID 38332153, 2024). "More importantly, cluster 2 exhibits a strong positive correlation with transcription factors WNT5A, WNT10A, GATA2, and FOSL2, all recognized for their involvement in tumor stemness." (PMID 38339238, 2024). "The E2F1-mediated inhibitory pathway of WNT5A expression and the CXCL12/CXC- chemokine receptor 4 (CXCR4) chemokine receptor signaling pathway facilitate the invasion of circulating tumor cells into the brain." (PMID 39328239, 2024). "For example, Wnt5a, Wnt5b, long non-coding ASMTL-AS1 in tumor cell exosomes all have the ability to activate YAP to promote tumor formation and development." (PMID 36123390, 2023). "TCAF2 in TPCs inhibited the expression and ion channel activity of TRPM8, promoting tumor cell EMT and metastasis via activation of the Wnt5a/STAT3 signaling pathway." (PMID 37635201, 2023). "Additionally, CUTL-1, a target of TGF-β involved in tumor invasion, may transcriptionally up-regulate Wnt5a, encoding the ligand of non-canonical Wnt pathway." (PMID 36675086, 2023). "Taken together, these data indicate that TCAF2 in TPCs induces Wnt5a secretion and activates STAT3, thus promoting tumor cell EMT and facilitating CRCLM." (PMID 37635201, 2023). "WNT5a expression was negatively correlated with tumor stages, LNM, and FIGO stages, but not with patients age, smoking and alcohol status, gross type, tumor location, and tumor diameter." (PMID 37335710, 2023). "Interestingly, WNT2b and WNT5a are highly expressed in NSCLC cells and stromal cells and may induce the polarization of tumor-associated macrophages (TAMs) to M2 status to strengthen the tumor progression." (PMID 37486552, 2023). "In the lung, however, metastatic cells are reactivated by aged fibroblasts through secreted sFRP1, which is an antagonist of Wnt5a, resulting in decreased AXL signaling, enhanced MER activation and tumor cell proliferation." (PMID 37296983, 2023). "Collectively, these data indicate that TCAF2‐induced Wnt5a secretion through inhibiting TRPM8 in TPCs, which activates the STAT3 signaling pathway in tumor cells, thus facilitating CRCLM." (PMID 37635201, 2023). "Mechanistically, TCAF2 inhibits the expression and activity of TRPM8, leading to Wnt5a secretion in TPCs, which facilitates EMT via the activation of the STAT3 signaling pathway in tumor cells." (PMID 37635201, 2023). "The overexpression of KLF2 affected WNT5A, WNT5B, and FZD-2 in the WNT signaling pathway, which regulates epithelial-mesenchymal transition involved in tumor metastasis." (PMID 36761967, 2023). "The secreted protein genes WNT5A, VEGFA, and SEMA3A, and the receptor genes AXL, TNFRSF10B and IGF1R were mainly expressed by tumor cells." (PMID 37823774, 2023).